ENSG00000291066 (novel transcript)
Synonyms: RRN3P1
Gene: Long non-coding RNA gene on chromosome 16 (21,796,004 to 21,820,656, reverse strand). Ensembl gene ENSG00000291066.
Gene Ontology:
Biological process: SRP-dependent cotranslational protein targeting to membrane, signal sequence recognition
Cellular component: signal recognition particle, endoplasmic reticulum targeting